FAM9B (family with sequence similarity 9 member B)
Description:
May play a role in meiosis.
Synonyms: TEX39B
Tractability: No criterion of Open Targets' tractability assessment is met for any kind of drug.
Gene: Protein-coding gene on chromosome X (9,024,232 to 9,295,682, reverse strand). Ensembl gene ENSG00000177138.
Subcellular location: Nucleus; Cytoplasm; Chromosome
Subcellular location (Human Protein Atlas): Nucleoplasm
Gene Ontology:
Molecular function: protein binding
Biological process: meiotic cell cycle; spermatid development
Cellular component: chromosome; cytoplasm; nucleus; synaptonemal complex
Homologues: Orthologues: macaque FAM9B (94% identical), chimpanzee FAM9B (82% identical), zebrafish sycp3 (25% identical), tropical clawed frog sycp3 (24% identical), mouse Xlr3b (19% identical), mouse Xlr3c (19% identical), mouse Xlr3a (18% identical), rat LOC100911047 (18% identical), mouse Xlr5b (17% identical), mouse Xlr5c (17% identical), mouse Xlr5a (17% identical), rat Xlr4a (17% identical), and 8 more. Paralogues in human: FAM9A (63% identical), FAM9C (51% identical), SYCP3 (28% identical).
Diseases named in the same sentence as FAM9B in open-access papers:
FAM9B is named in the same sentence as 4 diseases in open-access papers, as found by Europe PMC text mining. Sharing a sentence is not in itself a finding about the gene and the disease. The quoted sentences say what the papers report.
Infertility (3 papers, 2021 to 2024). "Deletion in FAM9B may be associated with a number of clinical conditions in males, such as infertility." (PMID 34507348, 2021). "In line with this, we found that numerous infertility-related DMR-associated genes are expressed during spermatogenesis (e.g., VPS37D, FAM9B [MIM: 300478], SLCO3A1, and CCDC200)." (PMID 38759652, 2024).
tumor (1 paper, 2022). "FAM9B and related genes have been shown to be upregulated in tumor cells and also induced by DNA damaging agents." (PMID 36006120, 2022).
FAM9B also shares sentences with these, for which no sentence is quoted: coronary atherosclerosis (1 paper); ischemic heart disease (1).